RPL11 (ribosomal protein L11)
Diseases named in the same sentence as RPL11 in open-access papers (continued):
Sharing a sentence is not in itself a finding about the gene and the disease.
cancer (continued). "We analyzed MDM2 and RPL11 expression pattern in different cancer cells using the Cancer Dependency Map (DepMap) Portal database." (PMID 36071402, 2022). "Our results reveal that the nucleolar stress response via RPL11 regulates the sensitivity of these cancer cells to topoisomerase inhibitors." (PMID 36555627, 2022). "Our screening for mutations and copy number changes identified six ribosomal protein genes as candidate cancer driver genes, including RPL5 and RPL11, which were previously reported in cancer." (PMID 28147343, 2017). "According to these criteria, five genes (RPL5, RPL11, RPS5 (uS7), RPS20 (uS10), RPSA (uS2)) were significantly mutated in four different cancer types." (PMID 28147343, 2017). "Most interestingly, both RPL11 and RPL5 present inactivating mutations and emerge as candidate cancer drivers in the same cancer type (SKCM)." (PMID 28147343, 2017). "DBA variants in patients with cancer/MDS refer mainly to RPS19, RPL35A, RPL11, RPL5, RPS17, and GATA1 genes (18%, 13%, 10%, 5%, 3%, and 3%, respectively; 49% unknown)." (PMID 38002903, 2023). "Importantly, it has been shown recently that an RPL11-mediated nucleolar stress response regulates the sensitivity of cancer cells to topoisomerase inhibitors, including topotecan." (PMID 36838813, 2023). "As a decreased expression of RPL11 leads to reduced sensitivity to topoisomerase inhibitors, the development of drugs that increase RPL11 expression could contribute to increasing the efficacy of topoisomerase inhibitors and overcoming resistance in cancers." (PMID 36555627, 2022). "Therefore, the identification of MDM2-binding RPL11-mimetics would be valuable for anti-cancer therapeutics." (PMID 36071402, 2022).
cancer (continued). "Further research is needed; however, cancer patients with both high RPL11 and low APTX expression may display higher treatment sensitivity to topoisomerase inhibitors than those with either high RPL11 or low APTX expression alone." (PMID 36555627, 2022). "In the present study, we investigated whether the nucleolar stress response via RPL11 is involved in the sensitivity of cancer cells to topoisomerase inhibitors." (PMID 36555627, 2022). "Our work also shows that RPL11-mediated nucleolar stress response is crucial for sensitivity to topoisomerase inhibitors, suggesting that RPL11 expression may be a potential biomarker for predicting topoisomerase inhibitor sensitivity in cancer." (PMID 36555627, 2022). "A recent study identified six ribosomal protein genes as potential cancer drivers in five different cancer types: uL18/RPL5, uL5/RPL11, uL23/RPL23A, uS7/RPS5, uS10/RPS20, and uS2/RPSA82." (PMID 29674660, 2018). "We screened mutation and copy number data of respectively 4926 and 7322 samples from 16 cancer types and identified six altered genes (RPL5, RPL11, RPL23A, RPS5, RPS20 and RPSA)." (PMID 28147343, 2017).
cancer (continued). "Recently, several RPs, including RPL5, RPL11, and RPS14, have been found to associate with TAp73, but not ΔNp73, to overcome MDM2-mediated inactivation, leading to TAp73-induced cancer cell apoptosis." (PMID 32198344, 2020). "Previous evidences demonstrate that c-Myc and its regulated ribosomal biogenesis by ribosomal RNA synthesis and processing are critically involved in cancer progression and ribosomal protein L5 (RPL5), RPL11, and RPL23 regulates apoptosis in response to ribosomal stress." (PMID 31574980, 2019). "By contrast, for patients without reduced RPL11 expression, topoisomerase inhibitors may be effective in cancer patients." (PMID 36555627, 2022). "RPL11 and RPL5 may inhibit cancer cell proliferation and induce apoptosis." (PMID 32483207, 2020). "However, based on recent findings, there is no direct evidence for RPL11 to contribute to one or a few specific cancer subtypes, implying that it can only differentiate between the normal control and the other six subtypes of cancers." (PMID 29152097, 2017).
tumor (39 papers, 2010 to 2026). "Consistent with cells of DBA patients, we speculate that cells of Rpl11-deficient zebrafish embryos may carry characteristics of tumor cells." (PMID 24341334, 2013). "RPL5 and RPL11 collaborate to suppress c-Myc expression via miRNA-mediated mRNA degradation, thus acting as tumor suppressors." (PMID 40864769, 2025). "The tumor suppressor PICT1 interacts with RPL11 and other RPs to maintain their nucleolar localization." (PMID 34831461, 2021). "RPS6, RPS19 and RPS25 helps in the transcription initiation of viral genes while RPL5 and RPL11 acts as tumor suppressors by degrading the mRNA of c-myc, through RNA induced silencing complex (RISC)." (PMID 29568375, 2018). "RPL11 retention in the nucleolus is important for tumor progression." (PMID 34831461, 2021). "For example, one study found decreasing the tumor suppressors RPL5 or RPL11 resulted in a reduction in ribosome content and translation capacity, causing cells to progress at a lower rate through all stages of the cell cycle thus resulting in decreased proliferation without cell cycle arrest." (PMID 29466962, 2018). "Combined with its specific expression in exosomes, RPL11 may be an effective biomarker for tumor liquid biopsy, validating our prediction." (PMID 29152097, 2017). "Additionally, RPL11 suppresses tumor growth by inhibiting c-Myc translation." (PMID 40895534, 2025). "Our results presented here showed that RPL11 might be a potential tumor activator in NSCLC." (PMID 36869281, 2023). "Through these networks, Rpl11 may play critical regulatory roles in cell development, proliferation, and apoptosis, nervous system development, embryonic development, immunological disease, and tumor pathology." (PMID 24341334, 2013).
tumor (continued). "In cancerous cells, the ubiquitination of specific RPs can promote tumour invasion, tumour metastasis, and resistance to chemotherapy treatment, thereby contributing to tumour progression (see sections on RPL5, RPL11, RPS3, and RPL23a)." (PMID 40940922, 2025). "For example, alterations in RPs such as RPL5 (uL5), RPL10 (uL16), RPS15 (uS19), RPL11 (uL15), and RPL22 (eL22) have been described in 10–40% of multiple tumor types." (PMID 31590378, 2019). "The upregulation of RPL5 or RPL11 is regulated through the depletion of MID1IP1, and the depletion of RPL5 and RPL11 activates c-Myc in MID1IP1-depleted HepG2 and Huh7 cells, suggesting that RPL5 and RPL11 are responsible for the regulation of c-Myc as tumor suppressors." (PMID 40864769, 2025). "Moreover, alterations of RPL5, RPL10, RPS15, RPL11, and RPL22 ribosomal proteins have been described in 10 to 40% of tumor types." (PMID 33462193, 2021). "Importantly, some RP genes (e.g., RPL5, RPL11 and RPS20) are known to be tumor-suppressor genes, which is not the case for GATA1." (PMID 35328001, 2022).
infection (4 papers, 2017 to 2022). The state of being infected such as from the introduction of a foreign agent such as serum, vaccine, antigenic substance or organism. "In contrast, the biological processes downregulated with infection include ribosomal biogenesis (Rpl3, Rpl37, Rps5, Rpl11, Rplp1, Rpl28, Rpl19, Rps28, Rps14)." (PMID 35789215, 2022). "We next investigated the interaction between RPLs (RPL11 and RPL23) and MDM2 during different time points post-infection (8 hpi and 24 hpi)." (PMID 29259342, 2017).
immune dysfunction (1 paper, 2025). "Therapeutically, targeting the BPA–RPL11 interaction (e.g., via small-molecule inhibitors) or restoring RPL11 expression may mitigate ribosomal stress and immune dysfunction in DR." (PMID 41384025, 2025).
inflammation (1 paper, 2025). Aberrant reaction of the microcirculation characterized by movement of fluid and leukocytes from the blood into extravascular tissues. "3.Immune dysregulation: RPL11 downregulation shifts immune cell populations, promoting retinal inflammation." (PMID 41384025, 2025).
metabolic disorders (1 paper, 2025). "Prior studies have linked ribosomal protein dysregulation—especially RPL11—to metabolic disorders: RPL11 downregulation in pancreatic β-cells impairs insulin secretion, while ribosomal stress in endothelial cells exacerbates diabetic macroangiopathy." (PMID 41384025, 2025).
RPL11 also shares sentences with these, for which no sentence is quoted: myelodysplastic syndrome (4 papers); melanoma (2); adenocarcinoma (1); amyotrophic lateral sclerosis (1); Bloom syndrome (1); bone marrow failure (1); Bowen-Conradi syndrome (1); cervical cancer (1); chronic lymphocytic leukemia (1); dementia (1); diabetic retinopathy (1); endometrial cancer (1); HCMV infection (1); imbalance (1); kidney (1); microcephaly (1); multiple myeloma (1); nasopharyngeal carcinoma (1); nerve sheath tumors (1); pancreatic cancers (1); pancreatic ductal adenocarcinoma (1); rapadilino syndrome (1); retinal degeneration (1); rhabdomyosarcoma (1); Treacher-Collins syndrome (1); virus infection (1); Werner syndrome (1).